PAX4 (paired box 4)
Diseases named in the same sentence as PAX4 in open-access papers (continued):
Sharing a sentence is not in itself a finding about the gene and the disease.
diabetes (continued). "We conclude that, whilst PAX4 is not essential for in vitro stem cell differentiation to SC-islets, both PAX4 haploinsufficiency and loss-of-function coding alleles increase the risk of developing diabetes by negatively impacting human beta cell development and insulin secretion." (PMID 37777536, 2023). "The transient diabetes phenotype observed in our patients suggests that beta cells can develop in humans in the absence of PAX4." (PMID 40614820, 2025). "Of note, the plasticity of islet cells conferred by PAX4 and ARX has become a major research focus in human diabetes research because their targeting may prompt the replenishment of β-cells." (PMID 41472147, 2025). "Both PAX4 and PAX6 have a well-established link to diabetes phenotypes." (PMID 30007277, 2018). "PAX4 overexpression blunted EAD, whereas the diabetes-linked mutant variant PAX4R129W did not convey protection." (PMID 26813254, 2016). "The coordinated regulation of distinct cellular pathways particularly related to ER homeostasis by PAX4 not achieved by the mutant variant PAX4R129W alleviates beta cell degeneration and protects against diabetes mellitus." (PMID 26813254, 2016). "Given the high prevalence of diabetes in the family and both maternal grandparents having diabetes, we evaluated measures of insulin resistance (HOMA-IR) and beta cell function (DI) in family members with and without the PAX4 p.Tyr186X variant." (PMID 37777536, 2023). "Additionally, previous studies also showed that PAX4+/− mice exhibit insulin-producing β cells and do not develop diabetes, indicating that a single copy of PAX4 is sufficient to promote normal β cells development and function." (PMID 29950431, 2018). "However, in contrast to Pax4 misexpressing mice, we did not observe oversized islets or diabetes in adult mice misexpressing Nkx6.1." (PMID 23382704, 2013).
type 2 diabetes (25 papers, 2013 to 2026). "Genetic variants in or near the CDKAL1, KLF9, GP2, ALDH2, and ITIH4 genes are associated with obesity and genetic variants in or near the GDAP1, PTF1A, SIX3, ALDH2, and PAX4 genes are specifically associated with type 2 diabetes in East Asians." (PMID 37749090, 2023). "The coding variant (p.Arg192His) in the transcription factor PAX4 is associated with an altered risk for type 2 diabetes (T2D) in East Asian populations." (PMID 37777536, 2023). "A coding variant of the PAX4 transcription factor (p.Arg192His) is uniquely associated with Type 2 Diabetes in East Asian populations." (PMID 37777536, 2023). "The evidence from the recent studies suggest that PAX4 is also crucial for mature beta cell expansion and survival, and that PAX4 mutations or polymorphisms are associated with both type 1 and type 2 diabetes." (PMID 24013263, 2013). "The TF PAX4 has been investigated in the contexts of both AD and type 2 diabetes (T2D), and is known to function as a key link in the common pathways of both diseases." (PMID 41223260, 2025). "Although it is well established that PAX4 as a transcriptional repressor regulates glucose intolerance, hormone-directed homeostatic processes, and type 2 diabetes, this study is the first to demonstrate that PAX4 can also regulate glucose uptake." (PMID 31216190, 2019). "Pathogenic variants in PAX genes underlie diverse congenital disorders such as aniridia (PAX6), renal coloboma syndrome (PAX2), otofaciocervical syndrome with immunodeficiency (PAX1), Waardenburg syndrome (PAX3), maturity-onset diabetes of the young (PAX4), and tooth agenesis (PAX9)." (PMID 41751498, 2026). "Moreover, module M7, which is enriched for beta cell markers and type 2 diabetes GWAS candidates, highlights hub genes such as ZNF800, which is closely associated with PAX4, important in the development and differentiation of beta cells." (PMID 34554282, 2022). "PAX4, a transcriptional repressor, interacts with and represses the activity of transcription factors involved in glucose intolerance, hormone-directed homeostatic processes, and type 2 diabetes." (PMID 31216190, 2019). "Specifically, the type 2 diabetes-associated cyclin-dependent kinase inhibitor 2A, which strongly inhibits the proliferative cyclin-dependent kinase 4 (CDK4), was enriched in PAX4R129W islets whereas it was decreased in PAX4 islets." (PMID 26813254, 2016). "Interestingly, MAFA nuclear expression in both alpha and beta cells, and the percentage of alpha cells expressing PAX4 were found altered in a substantial proportion of patients with type 2 diabetes." (PMID 24013263, 2013). "Similarly, the individual with the PAX4 PTV had adult onset diabetes (age at diagnosis 56 years)." (PMID 29207974, 2017).
MODY (24 papers, 2012 to 2025). "We recently demonstrated that variants in BLK, KLF11, and PAX4 reported to cause MODY are common in the population, have limited co-segregation, and lack enrichment in MODY cases compared to controls." (PMID 40779032, 2025). "Third, it describes a patient carrying two predicted deleterious variants in different MODY genes (PAX4 p.Ser67Arg and PDX1 p.Gly137Cys)." (PMID 41262822, 2025). "For example, rare PAX4 mutations were first identified in Thai MODY probands (designated MODY9), but they are seldom found in those of European descent." (PMID 29871606, 2018). "PAX4 with the R192H polymorphism has diminished repressor function on its target insulin and glucagon promoters when compared to wild-type Pax4, and it is associated with both MODY and early-onset T2D." (PMID 37175989, 2023). "MODY9 (OMIM # 612225) is a rare type of MODY, caused by a mutation in the Paired box gene 4 (PAX4)." (PMID 36595822, 2022). "In India, targeted next-generation sequencing of 10 MODY genes in 56 patients identified potentially pathogenic variants in HNF4A, GCK, HNF1A, PDX1, HNF1B, NEUROD1, and PAX4 in 11 individuals, suggesting a more complex etiological spectrum in this population." (PMID 41153735, 2025). "Of the 89 eDia3 patients, 10 (11.2%) carried likely pathogenic variants in genes (KLF11, GCK, ABCC8, PAX4, BLK and HNF1A) of MODY." (PMID 35921062, 2022). "Laver et al5 also demonstrated by variant— and gene‐level genetic evidence that BLK, KLF11, or PAX4 was not a cause of MODY, and they proposed that these three genes should be removed from MODY diagnostic genetic testing." (PMID 38095268, 2024). "We did not include BLK, KLF11 and PAX4 in our gene panel due to lack of strong genetic evidence supporting the gene-disease association for MODY." (PMID 34789499, 2022). "However, some authors have argued that there is insufficient evidence to support a causal role for BLK, KLF11, or PAX4 variants in MODY pathogenesis, and these genes should not be routinely included in diagnostic testing." (PMID 41153735, 2025). "Previous studies have shown that it modulates the expression of several MODY genes, including insulin, GCK, ABCC8, PDX1, and PAX4." (PMID 40148250, 2025). "Own4 reported 16 genes associated with MODY, including BLK, PAX4, and KLF11, but their genetic evidence was not well documented." (PMID 38095268, 2024). "To date, 14 disease genes for MODY are identified; most of them are transcription factors MODY1 (HNF4A), MODY3 (HNF1A), MODY4 (PDX1), MODY5 (HNF1B), MODY6 (NEUROD1/BETA2), MODY7 (KLF11), MODY8 (CEL), MODY9 (PAX4), MODY11 (BLK), and MODY14 (APPL1)." (PMID 31145732, 2019).
Hyperglycemia (11 papers, 2012 to 2025). An increased concentration of glucose in the blood. "Notwithstanding, despite the beneficial effects of PAX4, long term in vivo overexpression of Pax4 in β-cells can cause dedifferentiation of the β-cells leading to the development of hyperglycemia." (PMID 31817798, 2019). "In contrast, mice with paired box gene 4 (Pax4) deficiency exhibit the opposite phenotypic changes, showing both dramatic reduction in β cells and hyperglycemia-induced early death." (PMID 29880854, 2018). "Therefore, our next plan is to continue to feed these PAX4+/− rabbits, to observe whether the heterozygotes could develop hyperglycemia and other DM associated phenotypes, and to investigate the possibility of this rabbit model used for DM gene therapy." (PMID 29950431, 2018). "Typical phenotypes of growth retardation, persistent hyperglycemia, decreased number of insulin-producing β cells and increased number of glucagon-producing α cells were observed in the homozygous PAX4 KO rabbits." (PMID 29950431, 2018). "Compared with the WT littermates, the PAX4−/− rabbits showed severe hyperglycemia and high death rates (100%), and all the PAX4−/− rabbits died within 4 days after birth." (PMID 29950431, 2018). "DOX-mediated induction of Pax4 prevented hyperglycaemia development in BPTL animals up to 4 weeks after immunisation, whereas Pax4R129W induction partially reduced the hyperglycaemic incidence in mutBPTL mice." (PMID 26813254, 2016). "Nonetheless, sustained PAX4 expression promotes β-cell dedifferentiation and hyperglycemia, mimicking β-cell failure in diabetic patients." (PMID 26503027, 2015). "In mice, conditional overexpression of PAX4 in β-cells was shown to protect animals against streptozotocin (STZ)-induced hyperglycemia and isolated islets against cytokines induced apoptosis." (PMID 26503027, 2015). "Regeneration of the β-cell mass by aberrant expression of Pax4 in α-cell was able to transiently rescue hyperglycemia in young animals rendered diabetic by chemical treatment." (PMID 22919462, 2012). "Complete loss of Pax4 function results in the absolute lack of β cells and insulin, causing hyperglycemia at birth, and is lethal as shown in the Pax4 deficient mouse and rabbit models." (PMID 37175989, 2023). "A similar regulatory cross talk between HMG20A and PAX4 may also be operative in early stages of hyperglycemia, which is characterized by active beta cell adaptation." (PMID 29449530, 2018). "In conclusion, this is the first report of a PAX4 gene KO model in rabbits, including characteristics of growth retardation, persistent hyperglycemia, decreased number of insulin-producing β cells, increased number of glucagon-producing α cells and typical DM associated phenotypes." (PMID 29950431, 2018). "In addition, overexpression of PAX4 gene can stimulate β cell proliferation and increase their resistance to hyperglycemia induced apoptosis in adult islets." (PMID 29950431, 2018). "Furthermore, the PAX4−/− rabbits died soon after birth due to severe hyperglycemia, and finally all of them died within 4 days." (PMID 29950431, 2018). "Furthermore, Pax4 levels were also found elevated in islets derived from T2DM patients correlating with hyperglycaemia, indicating a potential adaptation of β-cell mass in response to insulin resistance." (PMID 22919462, 2012). "Herein, we investigated whether PAX4 and PAX4R129W could promote beta cell health, preventing the development of hyperglycaemia in the RIP-B7.1 mouse model of experimental autoimmune diabetes (EAD), and sought to characterise the PAX4-regulated pathways implicated in islet survival and expansion." (PMID 26813254, 2016). "In conclusion, strategies to fine-tune PAX4 expression levels may constitute a promising approach to simultaneously expand while blocking dedifferentiation of the functional β-cell mass with the aim to salvage hyperglycemia in diabetic patients." (PMID 26503027, 2015).
Hyperglycemia (continued). "Inactivation of Pax4 by CRISPR/Cas9 system leads to significantly stunted growth, hyperglycemia, and neonatal death within 4 days of birth." (PMID 37175989, 2023). "Conversely, transgenic mice overexpressing Pax4 exhibited a significative increase in Bcl-2 mRNA but not in Bcl-xL, and they were protected from streptozotocin-induced hyperglycemia." (PMID 39857806, 2025). "Mice lacking Pax4 develop severe hyperglycaemia and die within days of birth due to a lack of mature pancreatic cells." (PMID 39062676, 2024). "Consistent with previous reports exploiting the RIP-B7.1 model, 90–100% of immunised non-DOX-treated RIP-B7.1 mice bearing either the Pax4 or Pax4R129W transgene developed hyperglycaemia within 3 weeks, correlating with insulitis and beta cell destruction." (PMID 26813254, 2016). "These researchers found that Pax4 overexpression, but not Pax4R129W, protected animals from streptozotocin-induced hyperglycemia as well as mouse islets from cytokine-induced apoptosis; these protective effects were at least partially due to a three-fold increase in the expression of Bcl-2." (PMID 39857806, 2025). "Herein, we provide proof-of-concept that PAX4, but not PAX4R129W, preserves the BCM and delays the development of hyperglycaemia in the RIP-B7.1 mouse model of EAD." (PMID 26813254, 2016).
Obesity (7 papers, 2013 to 2022). Accumulation of substantial excess body fat. "Expression of TPH1 and PAX4 (a critical transcription factor in EC cell specification) is augmented in the duodenum and gastric antrum of obese subjects, while levels of plasma 5-HT and serum levels of the 5-HT metabolite, 5-HIAA, are associated with measures of human obesity." (PMID 30678223, 2019). "Jejunal EECs isolated from patients with T2DM also demonstrate downregulation in genes involved in EEC differentiation (including PAX4 and FOXA2) and in the GCG gene itself, indicating that jejunal GLP-1+ cell differentiation and number are negatively affected by both obesity and T2DM." (PMID 35503251, 2022). "We did not detect any significant change in PAX4 nuclear expression in alpha or beta cell from T2D patients, when compared with the subjects with obesity or control individuals." (PMID 24013263, 2013). "HMG20A regulates metabolism-secretion coupling genes in beta cells and could be also involved in beta cell plasticity through PAX4 and REST, regulating phenotypic changes needed for beta cells in order to respond to different physiological situations as pregnancy and obesity." (PMID 29449530, 2018).
type 1 diabetes mellitus (7 papers, 2016 to 2025). A chronic condition characterized by minimal or absent production of insulin by the pancreas. "Pax4 is also important for adult β-cell function and is linked to human pancreatic disease; mutations and common risk alleles in Pax4 have been linked to type 1 diabetes (T1D) and type 2 diabetes (T2D)." (PMID 30007277, 2018). "One could therefore wonder whether the Pax4-mediated conversion of somatostatin-producing cells into insulin-expressing cells could also occur in the gastrointestinal tract, an information of great importance for type 1 diabetes research." (PMID 35573999, 2022).
insulinoma (6 papers, 2012 to 2024). "Interestingly, insulinomas express truncated variants of PAX4 characterized by modified C-terminal domains with functional PD and HD." (PMID 28282933, 2017). "All these comparisons highlighted several genes regulated only by NeuroD1, such pax4, rfx6, insm1a/b, genes reported to be direct targets of Neurod1 in human insulinoma cell line, therefore validating our experiments." (PMID 35286299, 2022). "PAX4 is upregulated in human insulinomas and functions as a survival factor in rat insulinoma cells via Bcl-xL upregulation." (PMID 31614829, 2019). "The expression of the anti-apoptotic factor Bcl-xL is increased after overexpression of PAX4 in an insulinoma cell line as well as in isolated rat islets." (PMID 28282933, 2017). "Silencing PAX4 in insulinoma cell lines decreases the expression of anti-apoptotic factors concomitantly with the increase in spontaneous apoptosis as well as with higher sensitivity to cytokine-induced cell death." (PMID 28282933, 2017). "In contrast, silencing of PAX4 expression in INS-1E insulinoma cell line decreases the expression levels of Bcl-xL correlating with increased spontaneous apoptosis and higher sensitivity to cytokines-induced apoptosis." (PMID 28282933, 2017). "Ectopic expression of mouse Pax4 in either human or rat islets as well as in the mouse insulinoma MIN6 cell line conferred protection against cytokine-mediated cell death and promoted islet cell proliferation." (PMID 22919462, 2012). "Supporting the role of Pax4 in survival/maintenance of β-cell mass, repression of Pax4 in the rat insulinoma INS-1E cell line and in hematologic cell lines that express high levels of the transcription factor provoked apoptosis." (PMID 22919462, 2012). "In contrast, aberrantly high expression levels of Pax4 were detected in human insulinomas as well as lymphomas." (PMID 22919462, 2012). "In addition, the treatment of MIN6 mouse insulinoma cell line with recombinant PAX4 protein protects these cells from TNF-α induced apoptosis, with a concomitant increase in Bcl-xL expression." (PMID 28282933, 2017). "Although further studies are required to elucidate the physiological role of PAX4 in insulinomas, it is tempting to speculate that this transcription activator role of truncated PAX4 may be one of the underlying reasons of the uncontrolled cell proliferation." (PMID 28282933, 2017).
Insulin resistance (3 papers, 2019 to 2023). Increased resistance towards insulin, that is, diminished effectiveness of insulin in reducing blood glucose levels. "Epigenetic mechanisms also have an impact gene networks that are involved in insulin resistance and insufficiency as it controls genes like GLP1 receptor and Paired box 4 (PAX4) which are among the major genes that are associated with β-cell formation and functions." (PMID 31803711, 2019). "The genetic variants related to T2DM in Caucasians are mainly related to insulin resistance, but those in Asians, including Chinese, Japanese, and Koreans, are involved in insulin secretion (GLP1R, PAX4, HNF4A, SLC30A8, HHEX, CDKAL1, CDKN2A/B, and GCKR)." (PMID 35956399, 2022).
Autoimmunity (2 papers, 2016 to 2021). The occurrence of an immune reaction against the organism's own cells or tissues. "We conclude that PAX4 favours beta cell survival and regeneration in various deleterious inflammatory and high-grade inflammatory environments, such as autoimmunity, through the coordinated regulation of immune modulation, cell cycle, cell survival, ER homeostasis and DNA repair." (PMID 26813254, 2016). "Further, increasing ω-3 PUFAs levels (via supplementation or stimulating endogenous synthesis/interconversion) blocked the development of autoimmunity, prevented lymphocyte infiltration into regenerated islets, and sharply elevated the expression of the β-cell markers—PDX1 and paired box 4 (Pax4)." (PMID 34926582, 2021).
breast carcinoma (2 papers, 2016 to 2021). "Patients with high PAX4 expression levels demonstrated lower 5-year survival rates in HNSCC, gastric cancer and breast cancer." (PMID 27613842, 2016).
gastric cancer (2 papers, 2016 to 2021). A primary or metastatic malignant neoplasm involving the stomach. "Thus, we speculated that PAX4 may target miR-27b-3p in gastric cancer cells." (PMID 34162761, 2021).
melanoma (2 papers, 2016 to 2017). A malignant, usually aggressive tumor composed of atypical, neoplastic melanocytes. "On the other hand, PAX1 and PAX4 are silenced by DNA methylation in ovarian and cervical cancers and in melanoma, and may function as tumor suppressors." (PMID 28241446, 2017).